CCR7 (C-C motif chemokine receptor 7)
Diseases named in the same sentence as CCR7 in open-access papers (continued):
Sharing a sentence is not in itself a finding about the gene and the disease.
Immunodeficiency (11 papers, 2012 to 2026). Failure of the immune system to protect the body adequately from infection, due to the absence or insufficiency of some component process or substance. "Because certain types of immunodeficiency may be induced with anti-CCR7 therapy, additional research is required to develop alternative strategies, such as targeting CCR7 exclusively in cancer cells or inhibiting CCR7-associated signal transduction pathways." (PMID 36980764, 2023). "Although numerous studies have currently uncovered the expression changes and potential action mechanisms of CCR7 in various immune diseases, its specific functions in different disease stages and different cell subsets remain to be further explored in depth." (PMID 41481752, 2026). "Intriguingly, previous works have noted that CCR7 expression suppresses the immunodeficiency phenotype by activating the chemokine signaling in T follicular helper cells after SCI." (PMID 37106817, 2023). "The results suggested that CCR7 suppresses the immunodeficiency phenotype by activating the chemokine signaling pathway in Tfh cells." (PMID 36312035, 2022). "The study here provides a novel therapeutic strategy of MSCs/CCR7 infusion at a low dosage to give potent immunomodulation effect for clinical immune disease therapy." (PMID 25549354, 2014). "The study here provides a novel therapeutic strategy of MSCs/CCR7 infusion at a low dosage to give potent immunomodulatory effect for clinical immune disease therapy." (PMID 25549354, 2014). "Subsequent Western Blot experimental results also confirmed the high expression of ICAM1 and SELL in UC, further emphasizing the importance of CCR7 in the pathogenesis of UC.The research on CCR7 in the field of immune diseases still holds boundless possibilities." (PMID 41481752, 2026). "Six genes related to (a) immune checkpoints (n = 2; BTLA and CD6); (b) regulatory macrophages and T cells (n = 2; CCR7 and CD3D); and (c) immune deficiencies and unfavorable prognosis (n = 2; CD3E and FCGR2B) were down-regulated post-RT compared with pre-RT (statistical p-range: <0.0001–0.0415)." (PMID 36291815, 2022). "Because of the underlying immunodeficiency, patients with WAS are prone to recurrent infections, including chronic viral infections, which are often associated with expansion of effector memory T lymphocytes and CD8+ CD45RA+ CCR7− TEMRA cells." (PMID 25101082, 2014). "Altogether, the loss of CCR7 on CD56bright NK cells marks a phenotypic shift of CD56bright NK cells towards a CD56dimCD16+ NK cell-like phenotype, which strongly correlates with clinical parameters of HIV-associated immune disease." (PMID 23028633, 2012). "However, these mice were immunodeficient, and further research is required to assess whether an anti-CCR7 therapy could result in any kind of immunodeficiency, since the anti-CCR7 antibody could both eliminate normal naïve and central memory lymphocytes and inhibit their entry into SLO." (PMID 24305507, 2013).
lupus (11 papers, 2007 to 2025). "Specifically, two Treg subpopulations, the CCR7 and CD74 Treg subgroups, are associated with type I interferon-induced dysfunction in SLE patients, suggesting that specific pathways in lupus need to be targeted." (PMID 39294397, 2024). "Recent reports suggest that CCR7 was involved in the progression of lupus and its expression was increased in SLE patients." (PMID 34867947, 2021). "Nineteen probes for 16 lupus-relevant genes (Abca1, Apobec3, Ccr7, Ceacam3, Ets1, Foxp3, Hdac1, Ifng, Irf9, Itgam, Jhdm1d, Mmp9, Oscar, Slc4a1, Tbx21, and Tlr7) were identified from the database of male murine spleen." (PMID 30246031, 2018). "In a representative experiment, we found that, unlike CCR6, CCR7 and CXCR5, the surface expression of CXCR4 was substantially up-regulated on the surface of B cells of lupus mice compared with the control non-lupus mice." (PMID 25909640, 2015). "The analysis of peripheral blood B cells by flow cytometry showed that the surface expression of CXCR4 was up-regulated on the surface of B cells of lupus mice, whereas there was no detectable change in the surface expression of CCR6, CCR7 and CXCR5." (PMID 25909640, 2015).
osteosarcoma (11 papers, 2008 to 2024). A usually aggressive malignant bone-forming mesenchymal neoplasm, predominantly affecting adolescents and young adults. "Furthermore, the CCR7+ DC subset specializes in directing DC mobilization to lymphoid organs and exhibits increased migratory speed, potentially indicating a close association with the metastatic potential of osteosarcoma." (PMID 39359731, 2024). "One study found that lncRNA DARS-AS1 regulated miR-532-3p/CCR7 axis and facilitated progression of osteosarcoma." (PMID 35992869, 2022). "CCR7 mRNA expression has recently been correlated with metastasis free survival in osteosarcoma patients." (PMID 18215331, 2008). "In a recent retrospective osteosarcoma patient study, the mRNA expression of the receptors CXCR4, CCR7 and CCR10 by osteosarcoma tissue was linked to clinical outcome." (PMID 18215331, 2008). "miR-532-3p directly regulated CCR7 expression in osteosarcoma cell." (PMID 35422889, 2022). "Previous study demonstrated that miR-532-3p inhibited TSCC progression through regulating CCR7 and it suggested that CCR7 might play important roles in the development of osteosarcoma." (PMID 35422889, 2022). "miR-532-3p directly regulates CCR7 expression in osteosarcoma cell." (PMID 35422889, 2022). "It suggested that DARS-AS1/CCR7 axis might be one novel therapeutic target for osteosarcoma." (PMID 35422889, 2022). "In a second study which examined the cells within the osteosarcoma tumor, although CCR7 expression was rare in osteosarcoma cells themselves, it was found in infiltrating inflammatory cells, which might account for the low lymphatic metastasis rates of osteosarcomas." (PMID 35203305, 2022). "Further characterization of four DC subclusters based on CD14/CD163, cDC1, cDC2, and CCR7 marker positivity demonstrates a higher number of cDC2 found in the TME of metastatic lung lesions than in primary and recurrent osteosarcoma." (PMID 39359731, 2024). "The elevated expression of CD83, CCR7, and LAMP3 in mDCs was consistent with research on osteosarcoma." (PMID 39256364, 2024). "Our findings showed that DARS-AS1 expression was upregulated in osteosarcoma cells and tissues, and elevated expression of DARS-AS1 enhanced cell growth and invasion via regulating miR-532-3p/CCR7." (PMID 35422889, 2022). "CCR1, CCR2, CCR5, CCR7, CXCR4, CXCR5 and CX3CR1 were found to be expressed in 100% of the osteosarcoma samples tested." (PMID 18215331, 2008). "lncRNA DARS-AS1 promotes the progression of osteosarcoma by regulating miR-532-3p/CCR7; lncRNA BACE1-AS regulates the proliferation, migration, and invasion of osteosarcoma cells through the miR-762/SOX7 axis; lncRNA SNHG1 promotes osteosarcoma progression by upregulating S100A6 through miR-493-5p." (PMID 36388161, 2022).
ovarian carcinoma (11 papers, 2011 to 2023). A malignant neoplasm originating from the surface ovarian epithelium. "A further study confirmed the frequent CCR7 expression in ovarian carcinoma tissues and association with advanced tumor stage and lymph node metastasis." (PMID 35203305, 2022). "Chemokine receptor 7 (CCR7) is constitutively expressed in epithelial ovarian cancer." (PMID 26356073, 2015). "This suggests that CCR7 may be an effective target for limiting cell invasion in certain ovarian cancers." (PMID 25852822, 2015). "Furthermore, CCR7, which can be induced in response to hypoxia and is often constitutively expressed in epithelial ovarian cancer cells, has been shown to participate in EMT development, leading to cell migration and invasion." (PMID 25852822, 2015). "Both CCR7 and CXCR4 expression were independent prognostic factors for reduced survival from ovarian cancer." (PMID 35203305, 2022). "CCR7 and its ligand CCL19/21 participate in EMT development, thus promoting ovarian cancer metastasis." (PMID 26356073, 2015). "The role of CETP, CCR7, and SELL in ovarian cancer is less studied." (PMID 36704336, 2022). "Furthermore, in vitro studies using human ovarian epithelial cancer cells, SKOV-3, indicated that CCR7 expression was elevated under hypoxic conditions and activation by CCL21 increased EMT development and ovarian squamous carcinoma cell invasion." (PMID 35203305, 2022). "Whereas CD8+ CD45RO+ CCR7+ T cells are found in blood and have no suppressive function, CD8+ CD45RO+ CCR7+ IL-10+ suppressive cells are found intratumorally in ovarian cancer patients and they are believed to be induced by plasmacytoid DC." (PMID 33584708, 2020).
Arthritis (10 papers, 2019 to 2026). Inflammation of a joint. "Of them, circulating fibroblasts (podoplanin+CD45-CD3-CD19-CD4-CD8-CD56-CD66b-CD294-) co-expressing CDH11 and C-C Chemokine Receptor 7 (CCR7) were found exclusively in arthritis patients' blood." (PMID 41624850, 2026). "CCR4, CCR6, CCR7, CCR9, CXCR5, and CXCR6 deficiency ameliorated arthritis in CIA mice by suppressing the migration of Th17 cells (CCR4), DC (CCR7), and CD11b+ splenocytes (CCR9)." (PMID 36860872, 2023). "Chemotactic signals, such as recruitment of Ccr7+ T-cells via Ccl19 produced by macrophages, were also identified as a putative explanation for the dramatic increase in T-cells in Advanced arthritis (green arrow)." (PMID 37691918, 2023). "In addition, treatment of humanized CCR7 mice with the anti-human CCR7 monoclonal antibody 8H3-16A12 produced favorable prophylactic and therapeutic effects against arthritis." (PMID 37183207, 2023). "B-cell memory subsets that express relatively lower CCR7 are also increased in synovial fluid from oligoarticular JIA patients, suggesting that these cells also play a role in arthritis." (PMID 33042130, 2020). "With the same tendency, in BD patients with arthritis, CCR7+, CD4+CCR7+, and CD8+CCR7+ cell frequencies in whole cells were decreased after improvement." (PMID 31614573, 2019). "Higher arthritis disease activity was positively correlated with CTLA4, CD28 and CD45RA and negatively correlated with CCR7 in 2019, which was a mean of about 4 years post-infection that was not conserved in 2021, which was a mean of about six-years post-infection." (PMID 38873035, 2024). "CCR7 positive cells were decreased after improvement and positively associated with blood leukocyte levels, and CD4+CCR7+ and CD8+CCR7+ in whole PBL, CD4+CD62L- and CD8+CD62L- in lymphocytes population were correlated to the presence of arthritis symptoms of BD." (PMID 31614573, 2019). "In BD patients with arthritis in our data, the frequencies of CCR7-CD62L-CD4+, CCR7-CD62L-CD8+ effector memory T cells, and CCR7+CD62L+CD4+, CCR7+CD62L+CD8+ central memory T cells were not different compared to HC or RA in PBL whole cells and in lymphocytes populations." (PMID 31614573, 2019).
esophageal cancer (10 papers, 2013 to 2025). A primary or metastatic malignant neoplasm involving the esophagus. "Studies have shown that CCR7 expression is upregulated in various types of cancer, and high CCR7 expression has been associated with poor prognosis and aggressive cancer subtypes, including non-small cell lung, gastric, and esophageal cancers." (PMID 40299690, 2025). "Here, we investigated the relationship between CCR7 and let-7a miRNA expression as well as the underlying regulatory mechanism, in esophageal cancer cell lines, tumor tissues, and peritumor tissues of patients with ESCC." (PMID 36243683, 2022). "Using quantitative RT-PCR analysis, CCR7 mRNA expression was confirmed in all esophageal cancer cell lines, and the level of let-7a miRNA expression was also determined." (PMID 36243683, 2022). "In contrast, when CCR7 was expressed alone or in combination with elevated MUC1 or CCL21 in esophageal cancers, the presence of CXCR3 worsened the prognosis." (PMID 35203305, 2022). "The inhibitory effect of let-7a was determined by using synthetic anti-let-7a oligonucleotides in KYSE-590 esophageal cancer cells, which expressed a low level of CCR7 and a high level of let-7a in the wild-type." (PMID 36243683, 2022). "In a recent study, researchers examined role of CCR7 gene as a metastasis and prognosis indicator in patients with esophageal carcinoma." (PMID 30781353, 2019). "Therefore, the downregulation of let-7a miRNA is a factor contributing to increased CCR7 expression levels in esophageal cancer cells and the development of malignant tumors." (PMID 36243683, 2022). "Overall, there is a strong link between CCR7 expression and esophageal cancer metastasis to the lymph nodes with associated rapid cancer progression and poor survival." (PMID 35203305, 2022). "The expression of CCR7 was downregulated by let-7a miRNA in esophageal cancer cells." (PMID 36243683, 2022). "For instance, the C–C chemokine receptor type 7 (CCR7), located mainly on the membrane of mature dendritic and T cells, is capable of interacting with its specific ligand CCL21 to facilitate lymph node metastasis in esophageal cancer." (PMID 29599774, 2018).
glioma (10 papers, 2017 to 2025). A benign or malignant brain and spinal cord tumor that arises from glial cells (astrocytes, oligodendrocytes, ependymal cells). "In this present study, we demonstrated the functional expression of CCR5 on CD38+HLA-DR+CD8+ T cells and the presence of CD45RA+CCR7− underling CCR5+CD38+HLA-DR+CD8+ T-cell activation in patients with glioma." (PMID 31649684, 2019). "In pediatric and young adult gliomas, TRM cells with the CD45RO+CD69+CCR7− phenotype are present in tumor tissues and are linked to better patient prognosis." (PMID 39802636, 2025). "Their study demonstrated that CCR7 mediates TGFB1-induced migration of glioma cells through the activation of matrix metalloproteinase 2 (MMP2)/9." (PMID 34643804, 2022). "MFAP2 expression was also correlated with chemokine receptors in gliomas, such as CCR3, CCR7, CXCR4, and CXCR6, which were significantly associated with MFAP2 expression in both LGG and GBM." (PMID 36204318, 2022). "Moreover, glioma monocytes and macrophages can be identified based on the expression of Ly6c, Ccr2, Cx3cr1, Cd64, Mertk, Cd45, F4/80, Ccr7 and transcription factor Nr4a113." (PMID 32555306, 2020). "By QPCR, we observed elevated expression levels of both CCR7 and CCL21 in a cohort of 14 WHO grade IV GBM compared to 11 LGG patients (WHO grade I, II, and III gliomas)." (PMID 37314567, 2023). "CCL21 and CCR7 expression in human GBM tumors, therefore, correlates with glioma malignancy and patient survival." (PMID 37314567, 2023). "In the presence of glioma cells, this CD8+ T cell subset appears to facilitate the enhancement of effector molecules, including CD45RA+CCR7−, T-bet+, CD107a+, IFN-γ+, and granzyme B+." (PMID 31649684, 2019). "Patients' CCR5+CD38+HLA-DR+CD8+ T cells were further validated and shown to display increases in CD45RA+CCR7− and T-bet+ accompanied by substantial CD107-a, IFN-γ, and Granzyme B levels in response to glioma cells." (PMID 31649684, 2019). "In response to glioma, CCR5+CD38+HLA-DR+CD8+ T cells were activated with a coinciding increase in TEMRA+ (CD45RA+CCR7−)." (PMID 31649684, 2019). "We detected the surface expression of CD28, CD45RA, CD45RO, CCR7, and CD44 in CTL and found CD28, CD45RO, and CD44 were expressed in glioma CD133+ CSC-reactive CTL, whereas CD45RA and CCR7 were rarely expressed." (PMID 28881826, 2017).
acute lymphoblastic leukemia (9 papers, 2010 to 2024). Leukemia with an acute onset, characterized by the presence of lymphoblasts in the bone marrow and the peripheral blood. "Similar to acute lymphoblastic leukemia, primary CNS lymphoma cells expressed CCR7, with CNS entry being dependent on CCR7 and its ligand, CCL19." (PMID 35203305, 2022). "CCR7 is expressed in mature T-cell malignancies, such as adult T-cell leukemia/lymphoma (ATLL) and Sézary syndrome (SS), and enables the entry of acute lymphoblastic leukemia (ALL) cells to the central nervous system (CNS) where CCR7 promotes survival and proliferation." (PMID 33110606, 2020). "C-C Chemokine Receptor 7 (CCR7) mediates T-cell acute lymphoblastic leukemia (T-ALL) invasion of the central nervous system (CNS) mediated by chemotactic migration to C-C chemokine ligand 19 (CCL19)." (PMID 39273598, 2024). "The authors raised security concerns about this engineering strategy, as gain of function (GOF) mutations of the IL-7 receptor (CD127) are frequent in pediatric T cell acute lymphoblastic leukemia (T-ALL) and as CCR7 could play a role in tumor metastasis." (PMID 35211124, 2022). "The malignant B cells from CLL or acute lymphocytic leukemia (ALL) patients take advantage of the CXCR5/CXCL13 axis and the CCR7/CCL19 axis for resistance to TNFα-induced apoptosis via upregulation of paternally expressed gene 10 (PEG10) and subsequent stabilization of caspase-3 and caspase-8." (PMID 34947813, 2021). "MEC-1 (a B-CLL derived cell line) showed high expressions of both receptors whilst Nalm6 (pre-B Acute Lymphoblastic Leukemia derived cell line) and Reh (Acute Lymphoblastic Leukemia) cells had a similar level of CRAM but no CCR7." (PMID 21092185, 2010). "The chemokine receptor CCR7 interacts with CCL19 and mediates T-cell acute lymphoblastic leukemia (ALL) metastasis to the central nervous system." (PMID 24259307, 2013).
esophageal squamous cell carcinoma (9 papers, 2014 to 2025). Esophageal squamous cell carcinoma (ESCC) is a type of esophageal carcinoma (EC) that can affect any part of the esophagus, but is usually located in the upper or middle third. "In a previous study, we demonstrated the significant clinicopathological relationship and functional causality between C–C chemokine receptor type 7 (CCR7) expression and lymph node metastasis in patients with esophageal squamous cell carcinoma (ESCC)." (PMID 36243683, 2022). "Another meta-analysis of four studies examining the role of CCR7 expression in OS in patients with esophageal squamous cell carcinomas revealed that high CCR7 expression was correlated with a poorer prognosis (HR 2.06, 95% CI 1.56–2.71, p < 0.001)." (PMID 40299690, 2025). "Another study discovered that CCL21/CCR7 promoted esophageal squamous cell carcinoma lymph node metastasis." (PMID 36829431, 2023). "C–C chemokine receptor type 7 (CCR7) participates in chemotactic and metastatic responses in various cancers, including in esophageal squamous cell carcinoma (ESCC)." (PMID 36243683, 2022). "High CCR7 expression in esophageal squamous cell carcinoma tissue samples correlated with lymph node metastasis, higher tumor stage and decreased survival time." (PMID 35203305, 2022). "CCR7 mRNA was detected in 9/20 esophageal squamous cell carcinoma cell lines with CCL21 activating cell migration and pseudopodia formation." (PMID 35203305, 2022). "In a mouse model of esophageal squamous cell carcinoma, CCL21 activation of CCR7-expressing cells increased cell adhesion that had a higher lymph node metastatic behavior." (PMID 35203305, 2022). "In this study, we hypothesized that patients with esophageal squamous cell carcinoma (ESCC) have a close relationship between CCR7 expression and lymph node metastasis because a functional CCR7 on ESCC cells plays a crucial role in lymph node metastasis in response to CCL21/SLC." (PMID 24766770, 2014).